RIPK1 (receptor interacting serine/threonine kinase 1)
Diseases named in the same sentence as RIPK1 in open-access papers (continued):
Sharing a sentence is not in itself a finding about the gene and the disease.
tumor (continued). "Based on this, we developed a combination therapy of SM164 and sunitinib for tumor types with high expression of SPOP/RIPK1, and the efficacy was significantly better than that of sunitinib monotherapy." (PMID 41122967, 2025). "This inhibitor not only demonstrates robust RIPK1 inhibitory activity in vitro but also promotes the formation of tumor-suppressive T cell phenotypes, showing potential antitumor activity." (PMID 40301325, 2025). "For instance, in pancreatic ductal adenocarcinoma, elevated levels of RIPK1, RIPK3, and MLKL are associated with accelerated tumor progression." (PMID 39949740, 2025). "Of note, RIPK1 expression exhibits tumour type-specific heterogeneity, consequently enabling context-dependent protumor or antitumor functions dictated by distinct cancer lineages and cellular milieus." (PMID 41334873, 2025). "Here, we demonstrate that sensitized tumor cells fail to initiate inhibitory RIPK1 phosphorylation at site S25 upon T cell attack, thereby foregoing a pro-survival checkpoint early in TNF signal transduction." (PMID 41315176, 2025). "Pancancer analysis suggests that KIRC is the most representative cancer with abnormally high expression of SPOP and RIPK1, so we selected 786-O cells to construct a nude mouse xenograft tumor model." (PMID 41122967, 2025). "RIPK1 regulates tumour cell migration and invasion by interacting with proteins associated with the cytoskeleton, such as F-actin and vimentin." (PMID 41334873, 2025). "This work reports a RIPK1 degrader that serves as a chemical probe for investigating the scaffolding functions of RIPK1 and as a potential therapeutic agent to enhance tumor responses to ICBs therapy." (PMID 39681571, 2024). "Here, using PROTAC technology, the authors report the design and characterization of a RIPK1 degrader, enhancing anti-tumor immunity in preclinical cancer models." (PMID 39681571, 2024). "LD4172 has also demonstrated significant therapeutic efficacy in vivo by inducing RIPK1 degradation within tumors and exhibiting a synergistic effect on tumor growth inhibition when combined with anti-PD1 therapy." (PMID 39681571, 2024). "This work reports the first RIPK1 degrader that serves as a chemical probe for investigating the scaffolding functions of RIPK1 and as a potential therapeutic agent to enhance tumor responses to immune checkpoint blockade therapy." (PMID 38659866, 2024). "A 5-day treatment with LD4172 was sufficient to induce substantial degradation of RIPK1 in the tumor (1st column)." (PMID 39681571, 2024). "Along with the anti-tumour immunity of RIPK1 and RIPK3, a recent study demonstrated that exogenous injection of necroptotic cells to the TME induces RIPK-mediated secretion of cytokines." (PMID 38698968, 2024). "In summary, we developed an RIPK1 degrader with high degradation specificity in cells and tumor selectivity in vivo." (PMID 39681571, 2024). "Receptor-associated factor 2 (TRAF2) was identified as a gatekeeper of TNF cytotoxicity threshold in tumours, by suppressing RIPK1-dependent cell death." (PMID 37503572, 2023). "Immunohistochemical analysis of tumor tissues revealed that treatment with the RIPK1 inhibitor alone enhanced the infiltration of CD8+T cells within CMT-167 tumors." (PMID 37865804, 2023). "It was found that the induction of necroptosis in endothelial cells promoted the extravasation and metastasis of tumor cells, and these effects were reduced by the RIPK1 inhibitor Nec-1 or specific knockdown of RIPK3 in endothelial cells." (PMID 37217473, 2023). "Research has shown that necroptosis enhances CD8+ leukocyte-mediated anti-tumor immunity by activating RIPK1 and RIPK3 in the tumor microenvironment (TME)." (PMID 36836481, 2023). "It promotes tumor cell migration and inhibits Fas induced apoptosis by assembling caspase-8/RIPK1/FADD/cFLIP complex." (PMID 37171396, 2023).
tumor (continued). "Collectively, our study findings reveal a potential combined therapeutic strategy utilizing a RIPK1 inhibitor and PD-1 blockade to enhance anti-tumor efficacy." (PMID 37865804, 2023). "Given that tumor-associated TRIM28 induces CD8+T cell exhaustion through NF-κB signaling, we sought to assess RIPK1 as a potential therapeutic target in combination with immune checkpoint blockade." (PMID 37865804, 2023). "Consistent with this theory, in a TRAF−/− melanoma mouse model, tumor cells redirected the TNF signaling pathway to favor RIPK1-dependent necroptosis, enhance tumor eradication, and show a better response to anti-PD-1 therapy than the control group." (PMID 36635765, 2023). "Deleting RIPK1 in tumour cells lowered infiltration by immunosuppressive macrophages in tumours, promoting TNF-induced killing and improving ICBT response." (PMID 37503572, 2023). "We knocked out the expression of Prmt1, Ripk1 or Axl in a murine MC38 tumor cell line by gRNA-expressing vectors compatible with either Perturb-seq or CROP-seq." (PMID 36518525, 2022). "The study of the relationship between RIPK1 and disease, especially the relationship between tumor growth, requires highly specific RIPK1 inhibitions and animal models." (PMID 36249746, 2022). "The inhibition of the N-end rule pathway, which degrades RIPK1, can promote necroptosis and lead to tumor regression." (PMID 35884370, 2022). "More importantly, scCRISPR screen platforms enable us to determine the heterogeneous changes of gene expression in Prmt1, Ripk1 or Axl knockout (KO) tumor cells in the presence of immune attack, which cannot be easily assessed by bulk RNA-seq." (PMID 36518525, 2022). "Although GSK′547 is used to investigate the inhibitory effect of RIPK1 in mouse tumor models, its high conversion rate in human liver cells prevents it from being used as a clinical lead compound." (PMID 36249746, 2022). "FASLG-FAS interaction activated RIPK1 and produce necrosome and finally induced necroptosis in tumor cells." (PMID 35864548, 2022). "At this point, there is still a limited understanding of the specific involvement of RIPK1 in the tumor immune microenvironment." (PMID 36171264, 2022). "The differential analysis in normal breast tissue and tumor tissue revealed that, except for RIPK1, RIPK3, TNF, MAP3K7, and STAT3, all the other genes showed significantly differential expression in BRCA." (PMID 35686108, 2022). "In contrast RIPK1, RIPK3, and MLKL are widely expressed in human pancreatic ductal adenocarcinoma associated with robust manifestation of chemokines resulting in tumor promotion." (PMID 33567618, 2021). "In a study of GBM patients, ~30% of tumours exhibited high levels of RIPK1 expression and this correlated with adverse prognosis." (PMID 34099897, 2021). "The invasive-disease-free survival analysis demonstrated enhanced TNBC-specific survival rate in patients with higher tumor expression of RIPK1 (hazard ratio, 0.31; p = 0.065)." (PMID 33980862, 2021). "As we demonstrated that RIPK1 is dispensable for tumor necroptosis, it is unlikely that death factors including TNF are the key triggers in tumor necroptosis." (PMID 33976222, 2021). "Necroptotic cells were shown to promote the migration and invasion of HNSCC cells in vitro through releasing DAMPs and RIPK1 can activate the NF-κB pathway in tumour cells which can lead to increased migration, invasion and proliferation." (PMID 33602906, 2021). "Genetic inhibition of RIPK1 significantly exacerbated the pro-tumor effect of AQP1, while ectopic expression of RIPK1 notably blunted AQP1 signaling." (PMID 33980862, 2021). "RIPK3 deletion in this PDA model or pharmacological inhibition of RIPK1 induce the recruitment of activated immune cells and favored tumor rejection." (PMID 34490126, 2021).
tumor (continued). "In the mouse model used in this study, based on a genetically inducible tissue specific Kras-dependent oncogenesis, intact RIPK1/RIPK3 signaling favored the recruitment of an immunosuppressive tumor microenvironment." (PMID 34490126, 2021). "On the other hand, activated caspase-8 promotes the expression of RIPK1 (receptor-interacting serine/threonine-protein kinase 1), inhibits the activation of NF-κB pathway, and inhibits the proliferation of tumor cells." (PMID 35145900, 2021). "Taken together, our data indicate that the activation of RIPK1/RIPK3 within the tumor microenvironment promotes the synthesis of immunostimulatory cytokines, thereby activating anti-tumor immunity." (PMID 34419074, 2021). "Consistent with this notion, SMAC mimetics have been shown to induce RIPK1-dependent death of tumor cells." (PMID 32024820, 2020). "In this study, moreover, patients with low tumor expression of RIPK1, RIPK3, and MLKL proved to have worse DFS." (PMID 32742497, 2020). "The status of RIPK1 immunoreactivity in the cytoplasm of epithelial or parenchymal cells was significantly higher in CCA tissues than cholangiocytes adjacent to tumor tissues (p = 2.8312E-18) and cholangiocytes from normal liver tissues." (PMID 33036630, 2020). "Because this early checkpoint is regulated by ubiquitination of RIPK1, ubiquitin E3 ligases and deubiquitinases are critical regulators of this checkpoint and potentially, tumor cell survival." (PMID 32024820, 2020). "To test this principle, we activated Ripk1‐induced cell death in the three drug‐tolerant tumour lines (124, 133 and 136) using Riboxxol." (PMID 32419365, 2020). "The mRNA expression of RIPK1, RIPK3, and MLKL in tumor tissues was significantly correlated with each other (r = 0.46, P <0.001, between RIPK1 and RIPK3; r = 0.35, P <0.001, between RIPK1 and MLKL; r = 0.43, P <0.001, between RIPK3 and MLKL)." (PMID 32742497, 2020). "Riboxxol is a synthetic TLR3 agonist that triggers Ripk1 activation and that is well tolerated when administered systemically or via intra‐tumour injections." (PMID 32419365, 2020). "In SCCs, tumor tissues had significantly lower mRNA expression level of RIPK1 (P = 5 × 10-4), RIPK3 (P = 3 × 10-15), and MLKL (P = 1 × 10-5) compared to normal lung tissues." (PMID 32742497, 2020). "This study provided a clear illustration of the tumour promoting activity of RIPK1/RIPK3-mediated inflammation via myeloid-dependent immune suppression." (PMID 31416294, 2019). "Furthermore, polymorphisms of RIPK1 have been found to be associated with differences in disease progression and correlated with overall survival and disease-free survival, suggesting that evaluation of RIPK1 polymorphism may be useful as a prognostic biomarker for tumor development." (PMID 31766571, 2019). "GSK’963, a potent small molecule inhibitor of RIPK1, was tested in tumor-bearing mice for its ability to reduce acute toxicity associated with TNF signaling." (PMID 31803362, 2019). "RIPK1 signaling and NF-κB-induced transcription in dying tumor cells also increase cross-priming efficiency and anti-tumor immunity." (PMID 30961656, 2019). "RIPK1-mediated necroptosis is the other vital mechanism of photothermal therapy killing tumor cells, in addition to apoptosis and necrosis." (PMID 29880902, 2018). "Our data also show that the kinase activity of RIPK1 has a role in the ability of tumor nodules to form in the lung." (PMID 28151480, 2017). "The loss of kinase activity of RIPK1 and the complete loss of RIPK3 were found to be important in the ability of the tumor cells to form lung nodules." (PMID 28151480, 2017). "Necrostatin was also less active on cells expressing low levels of RIPK1 (from the primary tumor 148I and metastases 98L, 147L and 148L)." (PMID 27129149, 2016).
tumor (continued). "Although there are some exceptions, both Ripk1 and Ripk3 mRNA expression was well correlated with their protein expression across different tumor lines (P=0.0168 for RIPK1 and P=0.002 for RIPK3 by Spearman correlation coefficients)." (PMID 25675296, 2015). "Overall, these data suggest that direct targeting of I2PP2A/SET by FTY720 induces PP2A/RIPK1-dependent necroptosis through its kinase domain, leading to cell death and subsequent tumour suppression." (PMID 23180565, 2013). "This suggests that inhibiting RIPK1 in tumour cells may induce autophagic defects, increase apoptotic sensitivity, and emerge as a novel strategy to overcome autophagy-dependent chemoresistance in cancer." (PMID 41334873, 2025). "We observed that sensitized tumor cells fail to recruit sufficient levels of pro-survival checkpoint kinases TBK1 and IKKε to Complex I, resulting in the loss of inhibitory Ser25 phosphorylation and an increase in activating Ser166 phosphorylation on RIPK1." (PMID 41315176, 2025). "Overall, our RIPK1 phosphorylation results reveal a pattern in which sensitized tumor cells lose pro-survival S25 phosphorylation and gain cell-death-promoting S166 phosphorylation under conditions where non-canonical IKKs fail to be recruited to the TNFR1 complex upon TNF stimulation." (PMID 41315176, 2025). "Moreover, sensitized tumor cells exhibited a corresponding increase in RIPK1 S166 phosphorylation within the TNFR1 complex." (PMID 41315176, 2025). "As expected, ACT with EBVSTs treatment was effective in reducing tumor size of G9-depleted mice when compared to control vector cells and showed that the depletion of G9 indeed increased the necrosis (RIPK1) and decreased autophagy (LC3B) by 3.1- and 1.32-fold, respectively." (PMID 39910335, 2025). "In contrast, promoting RIPK1 activation by removing pro-survival phosphorylation checkpoints (pS25) while enhancing pro-death phosphorylation (pS166) offers a more targeted approach that holds the potential to bypass tumor survival pathways." (PMID 41315176, 2025). "Inhibition of RIPK1 significantly heightens the sensitivity of tumour cells to these signals." (PMID 41334873, 2025). "Cellular RIPK1-caspase-8-dependent apoptosis was enhanced by the use of SIRT1 inhibitors, suggesting that RIPK1 may promote apoptosis upon acetylation, thus affecting the biological behavior of tumor cells and influencing tumor development." (PMID 40305291, 2025). "Therefore, targeting RIPK1 represents a promising therapeutic approach to overcome immune checkpoint blockade resistance and convert tumours into an immunologically hot phenotype." (PMID 41334873, 2025). "Overall, our data suggest that early phosphorylation of TNFR1 signaling complex components is crucial for tumor survival under T cell challenge and indicate that manipulating RIPK1 checkpoints may be a viable strategy to enhance T cell–mediated killing." (PMID 41315176, 2025). "Moreover, IHC results showed that cotreatment with SM164 and sunitinib enhanced the expression of cleaved caspase-3, a marker of apoptosis, in tumor tissues, and this effect was attenuated upon RIPK1 knockdown." (PMID 41122967, 2025). "In addition, necroptosis involving RIPK1 and RIPK3 causes tumor cell death and modulation of immune responses in the tumor microenvironment (TME)." (PMID 40257494, 2025). "Moreover, clinical studies have demonstrated that RIPK1 is significantly downregulated in tumour cells of lymphoma patients, thereby enhancing their proliferative capacity." (PMID 41334873, 2025). "Importantly, recent studies have demonstrated that disruption of RIPK1 scaffolding can synergistically promote necroptosis and innate immune activation, fostering tumor immunogenicity." (PMID 41354733, 2025). "The dual roles of RIPK1: oncogenic vs. tumour-suppressive functions across human cancers." (PMID 41334873, 2025).
tumor (continued). "Similarly, RIPK1 (receptor‐interacting protein kinase 1)‐induced immunogenic cell death of tumor cells activates CD8+ T cells and augments checkpoint blockade efficacy in STSs." (PMID 41357670, 2025). "Notably, RIPK1 inhibition leads to the fusion of cytotoxic T cells with T helper cells into a Th1/Th17 cell phenotype, allowing anti‐tumour immunity to be activated to inhibit tumour growth." (PMID 38652105, 2024). "Given that 98.6% of LD4172 is bound to plasma proteins, it is plausible that LD4172 may be “piggybacking” on albumin accumulation in tumors, thereby achieving tumor-selective RIPK1 degradation." (PMID 39681571, 2024). "In the context of this review, it is worth noting that the tolerogenic phenotype exhibited by tumor-associated macrophages in PDA was reliant on RIPK1 but independent of RIPK3 and necroptosis." (PMID 38576612, 2024). "Furthermore, the knockdown or inhibition of RIPK1 has the ability to avoid krasg12d‐promoting tumour progression." (PMID 38652105, 2024). "Furthermore, we found that decreasing RIPK1 dosing frequency by 50% resulted in a similar tumor inhibition effect when combined with anti-PD1, suggesting that the safety profile of RIPK1 degraders can be further improved by optimizing the dosing regimen." (PMID 39681571, 2024). "In addition, anti‐PD‐1 efficacy was improved in a mouse tumour model by using Smac mimics to mediate RIPK1‐dependent cell death to activate the activity of NK cells and T cells in the TME." (PMID 38652105, 2024). "According to research, RIPK1 inhibitors can inhibit tumor growth and limit metastasis." (PMID 38750159, 2024). "TRIM28 also promotes chemokine-driven myeloid-derived suppressor cell recruitment in the tumor microenvironment by interacting with RIPK1 (receptor interacting serine/threonine kinase 1) and facilitating its K63-linked polyubiquitination, thereby activating the NF-κB signaling pathway." (PMID 39160596, 2024). "Thus, RIPK1 has been described as a checkpoint kinase that controls tumor immunity, and its inhibition can be regarded as a potential tumor therapy." (PMID 38553639, 2024). "This prolonged retention in the tumor could further mitigate potential toxicity concerns related to RIPK1 degradation in normal tissues." (PMID 39681571, 2024). "An article reported that necroptosis could enhance antitumor immunity by activating RIPK1/3 within the tumor microenvironment (TME)." (PMID 37663658, 2023). "Recent research has demonstrated that during tumor formation, tumor necroptosis might be induced by death factors to engage in the RIPK1 and RIPK3 pathways." (PMID 37274025, 2023). "Additionally, when combined with a Smac mimetic LCL-161, an IAP antagonist, quercetin or kaempferol synergistically induced RIPK1/RIPK3/MLKL-mediated necroptosis in CCA cells while sparing non-tumor cholangiocyte cells." (PMID 37513508, 2023). "Tumor cells may undergo classic necroptotic events under hypoxic conditions by either inhibiting RIPK1 and RIPK3 expression or reprogramming glycolytic metabolism." (PMID 37169000, 2023). "RIPK1 expression was higher in tumor tissues than in paracancerous tissues." (PMID 37516007, 2023). "However, activation of the necroptosis death pathway, a type of programmed necrosis death, has also been observed when incubating tumor cells with RIPK-1 inhibitor, NEC-1." (PMID 37513863, 2023). "Genes such as Ado, TRAF2, Rb1cc1, PRMT1 and RIPK1 regulate tumor sensitivity to TNF-α." (PMID 37732732, 2023).